CRP (C-reactive protein)
Diseases named in the same sentence as CRP in open-access papers (continued):
Sharing a sentence is not in itself a finding about the gene and the disease.
rheumatoid arthritis (continued). "This is especially important when using CRP to make decisions about management of chronic diseases such as rheumatoid arthritis, where small differences in CRP might influence the decision whether to use biologics." (PMID 41284612, 2025). "That said, it is interesting to note that whilst high CRP is present in a number of autoinflammatory diseases including rheumatoid arthritis, high CRP levels are not commonly associated with SLE." (PMID 40801960, 2025). "Monoclonal antibodies such as tocilizumab and sarilumab, which inhibit IL-6 receptor signaling, markedly reduce circulating CRP levels and have shown cognitive and fatigue benefits in inflammatory disorders including rheumatoid arthritis and post-COVID syndromes." (PMID 41373439, 2025). "In conclusion, this study is the first to demonstrate that serum lactoferrin and thioredoxin levels are positively correlated with fibrinogen, but not with other acute-phase proteins such as ferritin and C-reactive protein (CRP) in patients with rheumatoid arthritis." (PMID 40943137, 2025). "Similar to IL6R perturbation, IL-6 signaling downregulation through genetic perturbation in IL6 was associated with a lower risk of both polymyalgia rheumatica (odds ratio (OR) per 24% decrease in CRP of 0.76, 95% CI 0.65 to 0.89) and rheumatoid arthritis (OR of 0.87, 95% CI 0.79 to 0.95)." (PMID 40858837, 2025). "Although CRP is considered an important marker of inflammation, it is usually expressed in response to chronic inflammatory‐related disorders such as diverse infections, rheumatoid arthritis, and CVD." (PMID 39619950, 2024). "Patients with some systemic autoimmune disorders such as rheumatoid arthritis are at increased risk of developing AF154 and the severity of inflammation as measured by levels of C-reactive protein (CRP) correlates with the incidence of AF in conditions characterized by chronic inflammatory changes." (PMID 38827406, 2024). "Although CRP is known to increase inflammation, chronic developments, such as liver dysfunction or specific diseases (e.g. rheumatoid arthritis or lupus), could manifest normal-to-low serum levels." (PMID 38835014, 2024). "Similarly, the Lactobacillus strain seems to be a promising treatment intervention for other types of arthritis such as rheumatoid arthritis (RA), with a recent review and meta-analysis highlighting the potential of this strain in reducing CRP." (PMID 39064686, 2024). "The study demonstrated that, in addition to elevated C-reactive protein (CRP), rheumatoid arthritis, and the total number of affected angiosomes, a factor that independently predicts poor leg salvage is an incomplete pedal arch identified during pre-surgery angiography." (PMID 38337576, 2024). "In juxtaposition, CRP levels manifest differently in rheumatoid arthritis (RA)." (PMID 39554800, 2023). "TMJ inflammation is sometimes correlated with rheumatoid arthritis, and diagnosing the latter in the jaw requires an assessment of biomarkers such as rheumatoid factor, ani-citrullinated protein antibody, C-reactive protein, and erythrocyte sedimentation rate throughout symptom duration." (PMID 37241010, 2023). "With rheumatoid arthritis, CRP levels can even exceed the 50 mg/L threshold." (PMID 37763974, 2023). "Furthermore, research has shown a negative correlation between the expression of the CD200R molecule on macrophages and CRP levels in rheumatoid arthritis." (PMID 37761997, 2023). "Moreover, an angiopoietin 2 (ANGPT2) rs3020221 polymorphism was found to influence both CRP and ESR levels in rheumatoid arthritis patients." (PMID 37238156, 2023). "However, the clinical utility has also been called into question; for example, a substantial number of patients with rheumatoid arthritis flares have normal CRP values." (PMID 37476185, 2023). "None of the other tested immune and inflammation traits (C-reactive protein, fibrinogen levels, hemoglobin, and rheumatoid arthritis) showed evidence of a causal effect on pain." (PMID 37844115, 2023).
rheumatoid arthritis (continued). "CRP levels help investigate treatment strategies for rheumatoid arthritis." (PMID 39554800, 2023). "Metformin significantly reduces CRP in people with rheumatoid arthritis, PCOS, and T2DM." (PMID 37108132, 2023). "Elevated CRP concentrations are associated with cardiovascular disease and acute kidney injury (AKI) in surgical patients, with inflammatory rheumatic diseases such as rheumatoid arthritis and gout, and with incident venous thromboembolism (VTE)." (PMID 36297178, 2022). "One meta-analysis of randomized control trials in rheumatoid arthritis showed that NSAIDs can modulate CRP levels, which may be dependent on the drug’s mechanism of action." (PMID 35821205, 2022). "Also, APP, like C-reactive protein (CRP), helps to restore cytokine homeostasis; and its level rises to 1000-fold during inflammatory conditions such as rheumatoid arthritis, cardiovascular disease, and infections." (PMID 35525916, 2022). "p38-MAPK inhibitors have been associated with tachyphylaxis in patients with rheumatoid arthritis and other inflammatory diseases, in which early reduction in inflammatory markers such as C-reactive protein (CRP) did not persist despite continued treatment." (PMID 35982464, 2022). "In normal individuals, the concentration of CRP is below 10 mg/L which can increase several folds following bacterial infection and in certain diseases like rheumatoid arthritis, cardiovascular complications, and progressive tumors, hence increase in CRP levels is mostly associated with diseases." (PMID 35793325, 2022). "CRP could be induced during inflammatory conditions including rheumatoid arthritis, infection, and some cardiovascular diseases and CRP concentrations of serum would increase over 1000-fold during infection or suffering tissue damage." (PMID 36009776, 2022). "Similarly, a study from 2017 demonstrated a proportional CRP response based on joint size in rheumatoid arthritis patients when compared to the same number of different sized joints." (PMID 34063875, 2021). "Clinical reduction of serum levels of TNF-α and clinical disease activity scores in rheumatoid arthritis and C-reactive protein (CRP) in Crohn's disease have been reported, in response to invasive VNS-devices, which necessitates operative implantation with potential postoperative complications." (PMID 34135691, 2021). "In a previous randomized, double blind, placebo controlled clinical trials carried out on 90 patients affected by cardiovascular diseases and/or osteoarthritis and/or rheumatoid arthritis, the effect of krill oil on C-reactive protein (CRP) and on arthritic symptoms were evaluated." (PMID 34073184, 2021). "Moreover, the randomized-controlled TARA (Trial of Atorvastatin in Rheumatoid Arthritis) study demonstrated that the addition of atorvastatin to conventional treatment improved disease activity and reduced CRP levels as well as tender joint counts." (PMID 32370139, 2020). "Also, fish oil enriched with LC ω-3 PUFA can reduce the amounts of C-reactive protein (CRP) and pro-inflammatory cytokines, and thus, reduce the risk of inflammatory diseases, such as rheumatoid arthritis." (PMID 33317025, 2020). "Furthermore, pre-diagnostic levels of plasma CRP and IL-6 are associated with a higher risk of Crohn’s disease; and TNFR2 level, a proxy for TNF-α, is associated with higher risk of rheumatoid arthritis up to 12 years prior to disease symptoms." (PMID 33259491, 2020). "Nevertheless, in pathologic conditions, this agent did not cause considerable changes in CRP levels in women who had rheumatoid arthritis (RA)." (PMID 32175075, 2020). "Indeed, studies in rheumatoid arthritis have demonstrated that C-reactive protein (a blood marker of inflammation) correlates negatively with both endothelial-dependent and endothelial-independent microvascular function." (PMID 29197931, 2018).
rheumatoid arthritis (continued). "Moreover, increased expression of SLC7A5 by peripheral monocytes from rheumatoid arthritis (RA) patients positively correlates with clinical parameters, such as CRP and ESR, suggesting that the SLC7A5-mediated AA influx is related to inflammatory conditions." (PMID 29422900, 2018). "Moreover, correlations between the increases of ADA levels and other inflammatory markers such as C-reactive protein (CRP) have been reported in diseases with inflammatory components such as gestational diabetes mellitus or rheumatoid arthritis." (PMID 28594948, 2017). "CRP was also detected in synovial biopsies from patients with rheumatoid arthritis." (PMID 24799767, 2014). "In clinically active human rheumatoid arthritis, levels of CRP are found to be increased." (PMID 25114906, 2014). "Another interesting approach is the antisense oligonucleotide ISIS-CRPRx, which reduces the CRP production in the liver and is currently tested in a phase 2 study on patients with rheumatoid arthritis, according to the manufacturer's website with promising success." (PMID 24808639, 2014). "A role for CRP in autoimmune diseases was suggested years ago when it was found that CRP was deposited in the nuclei of cells in the synovium of rheumatoid arthritis patients and localized with polymorphonuclear cells in vasculitis and experimental allergic encephalomyelitis." (PMID 24167754, 2013). "Also, high levels of MIF showed good correlation with CRP in the sera from patients with rheumatoid arthritis." (PMID 23451183, 2013). "Fibrates reduce C-reactive protein (CRP) and IL-6 in patients with Rheumatoid Arthritis, and we speculate that the beneficial effects of PPARα ligands may be related to augmented lymphocyte TRB3 expression." (PMID 24490110, 2013). "Therapeutic practice is evolving in rheumatoid arthritis with the introduction of biologic agents which provide rapid, profound and sustained suppression of disease activity in correspondence with a marked reduction in CRP levels." (PMID 18983663, 2008). "Interestingly, anti-chondroitin sulphate C IgM antibody levels showed inverse correlation both with the Disease Activity Score (DAS) 28 scores and C-reactive protein (CRP) levels in rheumatoid arthritis." (PMID 18789149, 2008). "Plasma pyridoxal 5'-phosphate and ΔtHcy levels were related to CRP in patients with rheumatoid arthritis, thus CRP could be a potential targets for vitamin B6 supplementation." (PMID 16277693, 2005). "Finally, conditions characterized by autoimmune responses and inflammation, particularly prevalent in women like systemic lupus erythematosus and rheumatoid arthritis, may elevate CRP levels." (PMID 40905016, 2025). "Musculoskeletal bleeding is common in patients with AHA and some patients may also have other autoimmune diseases, such as rheumatoid arthritis, which could contribute to an increase in white blood cells and elevated CRP levels and influence the physicians’ diagnoses." (PMID 41220543, 2025). "Erythrocyte sedimentation rate (ESR) and C-reactive protein (CRP) are widely used as biomarkers in the assessment of rheumatoid arthritis (RA), reflecting the inflammatory component of the disease." (PMID 40095875, 2025). "In rheumatoid arthritis (RA), for example, disease activity and treatment response are assessed based on the levels of CRP (or erythrocyte sedimentation rate) in combination with physical assessment such as inflamed or tender joint counts." (PMID 40856619, 2025). "Preoperatively, the patient had elevated ESR (erythrocyte sedimentation rate) and CRP (C-reactive protein), In the acute stage of rheumatoid arthritis, there may be a rise in ESR and CRP values and there were no signs of infection such as obvious redness and swelling in the hip joint." (PMID 40171003, 2025). "Serum CRP levels are commonly used in rheumatoid arthritis (RA) as an alternative marker of systemic inflammation." (PMID 38915456, 2024).
rheumatoid arthritis (continued). "CRP is an acute-phase protein produced in the liver, mainly by the hepatocytes and blood CRP level correlates well with rheumatoid arthritis (RA) disease severity." (PMID 39327635, 2024). "There are no definitive diagnostic criteria for rheumatoid arthritis, and patients typically present with joint tenderness and swelling, morning stiffness, and abnormalities on laboratory tests such as elevated C-reactive protein or erythrocyte sedimentation rate." (PMID 38217541, 2024). "Although CRP could reflect the inflammatory status of the whole body, when a patient is combined with other chronic inflammatory diseases, such as rheumatoid arthritis, some cytokines such as interleukin 6 can act directly on muscle tissue, causing a decrease in muscle strength and mass." (PMID 37488531, 2023). "Indeed, it is recognized that viral infections may give rise to moderate increases in CRP values, usually of up to 25 mg/L, whereas CRP levels can even exceed the threshold of 50 mg/L during rheumatoid arthritis." (PMID 37630683, 2023). "In rheumatoid arthritis (RA) patients, higher serum ET-1 levels were detected when compared to controls, and were positively related to C-reactive protein (CRP) levels." (PMID 37749230, 2023). "Investigating the causal relationship between rheumatoid arthritis (RA) and atlantoaxial subluxation (AAS) and identifying and quantifying the role of C-reactive protein (CRP) as a potential mediator." (PMID 36589832, 2022). "Rheumatoid arthritis (RA) is an autoimmune disease of inflammatory joint damage, wherein C-reactive protein and autoantibodies including rheumatoid factor (RF) and anti-cyclic citrullinated peptide (anti-CCP) are rapidly elevated." (PMID 33461622, 2021). "In the newest set of classification criteria for rheumatoid arthritis (RA), ‘abnormal CRP and/or ESR’ is regarded as a separate item together with joint involvement, presence of autoantibodies and duration of symptoms." (PMID 34945133, 2021). "Anti-CRP Abs have been identified in other autoimmune diseases, such as systemic sclerosis (SSc), rheumatoid arthritis (RA), and Sjögren syndrome (SS) patients, although at a lower prevalence than in SLE patients." (PMID 33664737, 2020). "We also tested the influence of CRP lowering therapy in the context of an animal model of rheumatoid arthritis (RA), i.e. collagen-induced arthritis (CIA)." (PMID 33633738, 2020). "The erythrocyte sedimentation rate (ESR) and C-reactive protein (CRP) are traditional inflammatory markers that have been used to help assess the activity of inflammation in various diseases, such as systemic lupus erythematosus, rheumatoid arthritis, and vasculitis." (PMID 33243164, 2020). "According to the 2018 Chinese guideline for diagnosis and treatment of rheumatoid arthritis, ESR, CRP, RF, anti-cyclic citrulline antibody, swollen joint count, and tender joint count should be taken into account in the treatment of RA." (PMID 32595735, 2020). "Biomarkers of rheumatoid arthritis (RA) disease activity typically measure inflammation or autoimmunity (e.g. CRP, RF)." (PMID 30886991, 2019). "In a radiographic CT and MRI study of patients with rheumatoid arthritis (RA), mean CRP levels were between 10 and 20 mg/L, and the levels of CRP were also correlated with inflammation in the TMJ." (PMID 31687055, 2019). "In rheumatoid arthritis (RA), the levels of inflammation, as measured by C-reactive protein (CRP) can be 10-fold higher than in the general population." (PMID 29855349, 2018). "Disease Activity Score in 28 joints-C-Reactive Protein (DAS28-CRP) is a composite score to evaluate disease activity, and also treatment response of patients with rheumatoid arthritis (RA)." (PMID 28383442, 2017).
rheumatoid arthritis (continued). "Because serum LRG concentrations correlate well with disease activity in ulcerative colitis and rheumatoid arthritis (RA), this novel serum biomarker could be a promising surrogate for C-reactive protein when monitoring disease progression in ulcerative colitis and RA." (PMID 27378305, 2016). "The aim was to compare the effect of etanercept (ETN) and conventional synthetic disease-modifying anti-rheumatic drug (DMARD) therapy on serum amyloid A (SAA) levels and to determine whether SAA reflects rheumatoid arthritis (RA) disease activity better than C-reactive protein (CRP)." (PMID 27188329, 2016). "A double-blind controlled trial has shown that psychological interventions such as cognitive behavior therapy can improve biological markers of disease activity (ESR, CRP, RA factor) in rheumatoid arthritis patients." (PMID 27714662, 2016). "In rheumatoid arthritis (RA), C-reactive protein (CRP), and matrix metalloproteinase-3 (MMP-3) are widely used as serologic biomarkers, but they lack sufficient specificity or precision." (PMID 27209430, 2016). "C-reactive protein (CRP) is one of the biomarkers for the diagnosis and assessment of disease activity in rheumatoid arthritis (RA)." (PMID 25889630, 2015). "For example, inflammatory markers such as C-reactive protein (CRP) or erythrocyte sedimentation rate (ESR) may be used to select a dose in rheumatoid arthritis treatment or can form part of a clinical composite such as disease activity score (DAS) 28 and be used for the same purpose." (PMID 23012528, 2012). "For example, where access to effective, but expensive, biological therapies in rheumatoid arthritis is rationed on the basis of a DAS28-CRP clinical activity score, then two patients with identical underlying disease severity could be given, or denied, treatment on the basis of CRP genotype alone." (PMID 20877716, 2010). "CRP itself has never been reported as a susceptibility gene in rheumatoid arthritis and, although we did not perform a disease association study here, the allele frequencies we observe in our patient sets are very close to those widely reported elsewhere for non-rheumatoid arthritis patients." (PMID 20877716, 2010). "Because rheumatoid arthritis (RA) confers excess cardiovascular mortality, we determined the prevalence of these CRP levels among RA patients stratified on the basis of their RA disease activity." (PMID 19606218, 2009). "Thus, when inflammatory markers are unavailable, hemoglobin alone provides a practical and reliable surrogate for overall disease burden, while integrating it with C-reactive protein or erythrocyte sedimentation rate may further refine prognostic assessment in newly diagnosed rheumatoid arthritis." (PMID 41377557, 2025). "In the present study, we investigated the associations of two antioxidant defence proteins—lactoferrin and thioredoxin—with fibrinogen and other acute-phase proteins, such as ferritin and C-reactive protein (CRP), in patients with rheumatoid arthritis." (PMID 40943137, 2025). "ESR elevation and Hb reduction are commonly associated with inflammatory and autoimmune diseases, including rheumatoid arthritis, where increased ESR and C-reactive protein (CRP) levels correlate with disease activity." (PMID 40251683, 2025). "In comparison to patients with rheumatoid arthritis, those with SLE are more likely to exhibit ESR than CRP levels." (PMID 40095875, 2025). "Rheumatoid arthritis (RA) patients have elevated CRP levels, which indicate systemic inflammation." (PMID 40380042, 2025). "Numerous studies have reported that temperature (T), CRP, and WBC hold statistical significance in distinguishing TCM cold and hot syndromes in rheumatoid arthritis." (PMID 40669043, 2025). "Rheumatoid arthritis patients are characterized by elevated levels of pro-inflammatory cytokines such as TNF-α, IL-6, IL-1β, and CRP, which reflect heightened inflammatory activity." (PMID 40709173, 2025).